CGAS (cyclic GMP-AMP synthase)
Diseases named in the same sentence as CGAS in open-access papers (continued):
Sharing a sentence is not in itself a finding about the gene and the disease.
neurodegenerative disease (continued). "This review aims to provide a comprehensive overview of the current understanding of the cGAS-STING pathway in the CNS in health and disease, with a focus on its involvement in neuroinflammation, neurodegenerative diseases, cellular senescence, and potential therapeutic implications." (PMID 37941028, 2023). "Indeed, it plays a role in neurodegenerative diseases, such as AD/ADRD, and gap junctions facilitate transfer between cells of the cGAS/STING second messenger, cyclic GMP-AMP (cGAMP)." (PMID 36248795, 2022). "Targeting the mtDNA/cGAS/STING pathway to reverse the phenotypic changes of microglia and astrocytes may be a new strategy for the treatment of neurodegenerative diseases." (PMID 34943020, 2021). "The additional consequence of MNi formation is stimulation of the innate immune system’s cGAS-STING pathway, which further increases the importance of MNi formation as a biomarker of cellular malfunction and as a driver of degenerative diseases that increase with age." (PMID 33076531, 2020). "A deeper comprehension of the function of the cGAS-STING pathway throughout aging and whether its potential manipulation could aid in delaying senescence or curing neurodegenerative diseases may be conceivable with more focused research on specific brain regions." (PMID 39149145, 2024). "Selective cGAS-STING inhibitors may also be beneficial for neurodegenerative disease, but have not been used systemically in humans." (PMID 39156128, 2024). "Recently, cytosolic immunogenic nucleic acids sensing, for instance cGAS–STING pathway, has been increasingly recognized as a primary determinant and potent regulator in neuroimmunological diseases, neurological infections, neurodegenerative diseases, as well as neuro-oncology." (PMID 36793064, 2023). "Originally identified as a crucial component of the innate immune host-defense system, cGAS-STING signaling has more recently been recognized as a key pathway in the initiation and pathogenesis of inflammatory diseases, including cancer, autoimmune and neurodegenerative diseases." (PMID 37941028, 2023). "Additionally, the cGAS-STING pathway had been reported to be a promising therapeutic target in autoinflammatory, autoimmune, and degenerative diseases, indicating that inhibition of cGAS-STING might also be applicated in attenuating IR-induced lung injury." (PMID 35892659, 2022). "However, we must also note that activation of cGAS-STING signaling is not a single facilitator in neurodegenerative disease." (PMID 36172373, 2022). "Therefore, cGAS-STING signaling is sensitive to the cellular environment, thus this pathway can become chronically activated in the context of elevated inflammation and disrupted autophagy, as is common in many neurodegenerative diseases." (PMID 35741054, 2022).
bacterial infection (47 papers, 2019 to 2026). "Notably, a recent preprint study reported that ALDH2 negatively impacts host defense against bacterial infection, raising the possibility that cGAS loss‐induced ALDH2 activation may enhance host protection against bacterial infection." (PMID 41042077, 2025). "Accordingly, MTCH2 depletion decreases not only apoptosis sensitivity but also sublethal mitochondrial permeabilization during bacterial infection, mitochondrial DNA release into the cytosol and cGAS-STING activation under impaired caspases." (PMID 42056306, 2026). "Increases in cytosolic DNA from mitochondrial stress, viral and bacterial infections or damaged cells activate the cyclic GMP-AMP synthase (cGAS)-stimulator of interferon genes (STING) and TANK-binding kinase 1 (TBK1) pathway." (PMID 41432900, 2025). "During viral and bacterial infections in human myeloid cells, NLRP3 was tightly linked to the upstream cGAS-STING pathway, inducing NLRP3 inflammasome activation and coordinating lysosomal cell death (LCD) in a K+ efflux-dependent manner." (PMID 38195584, 2024). "Mitochondrial oxidative stress-induced release of mtDNA in bacterial infection mediated the secretion of type I IFNs via the cGAS-STING pathway and triggered activation of the NLRP3 inflammasome." (PMID 38195584, 2024). "Of note, the activation of cGAS-STING signaling pathway has pleiotropic roles in the bacterial infection process." (PMID 36825026, 2023). "The late response was observed in sting(−/−) larvae following LPS treatment, demonstrating the importance of Sting-induced immunity during bacterial infection by activating the cGAS–STING pathway." (PMID 36830693, 2023). "During intracellular bacterial infections, Brucella DNA is probably sensed via the cGAS-STING signaling pathway as a major bacterial component." (PMID 36560581, 2022). "Future studies will further clarify the regulatory rules of cGAS-STING in various bacterial infections." (PMID 36231006, 2022). "In the last decade, studies on cytosolic surveillance systems have advanced significantly, highlighting the key role of the cGAS-STING signaling pathway in bacterial infection." (PMID 36059529, 2022). "On the one hand, IFN-I induced by the cGAS-STING pathway can fight against bacterial infections and inhibit the overactivation of the immune response." (PMID 35095914, 2021). "With the resolution of these questions in the future, we expect to effectively control bacterial infection and protect the host from injury by fine-tuning the cGAS-STING signaling pathway." (PMID 35095914, 2021). "The cGAS-STING pathway can also affect the outcomes of bacterial infections by participating in the mediation of some important physiological or pathological processes such as blood coagulation and autophagy." (PMID 35095914, 2021). "Currently, most of the work regarding the relationship between the cGAS-STING signaling pathway and bacteria focuses on the controversial role of the cGAS-STING pathway during bacterial infection." (PMID 35095914, 2021). "In the last decade, a series of studies in cytosolic surveillance systems have made fruitful progress and demonstrated a critical role of the cGAS-STING signaling pathway in bacterial infection." (PMID 35095914, 2021). "Cyclic GMP-AMP synthase (cGAS) is arguably the most prominent DNA sensing receptor found in the cytoplasm with relevance during bacterial infections." (PMID 33178195, 2020). "Cytoplasmic DNA fragments, derived from endogenous chromosomal or mitochondrial DNA resulting from DNA damage or from exogenous viral or bacterial infection, are detected by specific DNA-sensing machinery, such as the cGAS-STING pathway." (PMID 32466233, 2020). "However, concomitant with increases in immune mediator production, RIG-I and cGAS expressions were markedly elevated following S. aureus challenge, supporting a role for these sensors during bacterial infection." (PMID 40135931, 2025).
bacterial infection (continued). "All these suggest the intricate interplay between bacterial infection and cGAS-STING responses." (PMID 36825026, 2023). "The activation of the cGAS-STING pathway in various bacterial infections." (PMID 35095914, 2021). "Are there any rules determining whether the cGAS-STING signaling pathway has protective or detrimental effects in various bacterial infections?" (PMID 35095914, 2021). "New ideas for treating bacterial infections may be discovered by reviewing the structure, signal transduction process, and role of the cGAS-STING pathway in bacterial infection and bacterial immunity." (PMID 35095914, 2021). "Importantly, STING is itself a PRR engaged by cyclic dinucleotides (CDNs) that are synthesized both during bacterial infection as well as by cyclic GMP-AMP synthase (cGAS), a cellular nucleotidyl transferase that is activated after binding to cytosolic DNA." (PMID 32733475, 2020). "Furthermore, stimuli other than cGAS induced-cGAMP, including cyclic dinucleotides (CDNs) [cyclic diGMP, cyclic diAMP], and ER stress, which could be induced by bacterial infection, can also activate STING." (PMID 36825026, 2023). "Building on this information, it is likely that the liberating of mtDNA into the cytosol may represent a universal mechanism to activate the cGAS-STING pathway during intracellular bacterial infection, albeit further experimental evidence was required to confirm this notion." (PMID 35604097, 2022). "Furthermore, the cGAS-STING pathway is widely involved in various bacterial infections." (PMID 36231006, 2022). "Furthermore, they suggest, for the first time, the idea that BCAP can be considered a key molecule at the center of a positive feedback mechanism that could be implemented, for example, by cells with intracellular bacterial infections, which activate both the cGAS and Toll-like pathways." (PMID 40806167, 2025). "While the cGAS-STING pathway is well established in antiviral defense through sensing cytoplasmic DNA, its role in bacterial infections remains complex." (PMID 40697819, 2025). "Emerging evidence suggests that the cGAS-STING signaling pathway, beyond its antiviral functions, also plays a significant role in host defense against bacterial infections." (PMID 40697819, 2025). "Recently we demonstrated that macrophages isolated from TG2 knockout mice displayed an upregulation of the cGAS/STING/TBK1 pathway, the main innate immunity routes involved in the early defence against bacterial infections." (PMID 36923406, 2023). "The cyclic guanosine monophosphate-adenosine monophosphate (cGAMP) synthase (cGAS)/STING system is a therapeutic target for IFN-related inflammatory and bacterial infections." (PMID 37261340, 2023). "As a DNA sensor system, the cGAS-STING pathway was first discovered as a mediator of type I IFN inflammatory responses in immune cells to defend against viral and bacterial infections." (PMID 35235096, 2023). "Although cGAS can be activated by bacterial DNA and STING can be activated by bacterial-derived CDNs, the roles of cGAS and STING during bacterial infection are complicated." (PMID 37247757, 2023). "Although the role of the cGAS-STING pathway in favoring antiviral innate immune response has been extensively investigated, its role during bacterial infection is not fully understood." (PMID 35604097, 2022). "cGAS-cGAMP-STING pathway plays a significant role in host defense against viral and bacterial infection." (PMID 31120925, 2019). "Despite its relevance to viral and bacterial infections, cell death, and genome instability, the lack of specific live-cell reporters has precluded spatiotemporal analyses of cGAS-STING signalling." (PMID 39984755, 2025).
bacterial infection (continued). "In human myeloid cells, the cGAS-STING pathway was necessary for cytoplasmic DNA-induced NLRP3 activation during viral and bacterial infection; similarly, studies have shown that the STING-NLRP3 axis is critical for the pro-inflammatory response induced by Chlamydia trachomatis and aged macrophages." (PMID 38195584, 2024). "Interestingly, a recent work showed that TG2 is involved in the host’s inflammatory response during bacterial infections, being able to modulate the type I Interferon (IFN I) production through the cGAS/STING pathway." (PMID 36923406, 2023). "Apart from this last study, there are few reports on the impact of the absence of STING (and/or cGAS) in the control of bacterial infections." (PMID 37261352, 2023). "The cyclic GMP-AMP synthase (cGAS)-stimulator of interferon genes (STING) pathway has recently been identified as a pattern recognition receptor (PRR), which functions as a cytosolic double-stranded DNA (dsDNA) sensor during viral or bacterial infection 17,18." (PMID 37554263, 2023). "cGAS and STING detect bacterial genomic DNA and bacterial cyclic dinucleotides (CDNs) present in the cytoplasm, respectively, and thus affect the outcome of intracellular bacterial infection." (PMID 36231006, 2022). "It had become known that the cGAS-STING pathway is involved in the detection of cytosolic DNA, which elicits an innate immune response involving a robust type I interferon response against viral and bacterial infections." (PMID 36569852, 2022). "Thus, the cGAS-STING signaling pathway is more complex and diverse in bacterial infections." (PMID 36231006, 2022). "Additionally, the cGAS-STING pathway has also been involved in bacterial infections, but it does not always defend against bacteria, sometimes promoting their replication and survival." (PMID 35095914, 2021). "Thus, these candidates may affect other pathways in addition to the cGAS-STING pathway, leading to the inhibition of IFN-β production triggered by RNA viral and bacterial infection." (PMID 31539404, 2019). "Moreover, unlike its protective effect against viruses, the activity of the cGAS-STING signaling pathway in bacterial infection may not always be protective." (PMID 35095914, 2021). "Therefore, a better understanding of the role of the cGAS-STING pathway in bacterial infection and bacterial immunity will be of great value in many areas of research, such as the development of small molecule drugs targeting the bacterial cGAS-STING pathway without adverse effects on the host." (PMID 35095914, 2021). "The cGAS-STING pathway senses viral and bacterial infection, although it can also be triggered by non-infectious cellular stresses that elicit the release of DNA into the cytosol." (PMID 34111399, 2021).
cardiovascular diseases (34 papers, 2020 to 2026). "The major cytosolic DNA sensor cyclic GMP-AMP synthase (cGAS) has emerged as a key mediator of inflammation that underlies cardiovascular disease." (PMID 37548012, 2023). "Thirdly, besides mediating inflammation, cGAS also participates many other cell process, such as apoptosis and autophagy 45,46, which further underlies the critical role of cGAS-STING pathway in cardiovascular diseases." (PMID 37554263, 2023). "In addition, aging and aging-related diseases such as cardiovascular disease and metabolic disease, in which mitochondrial damage and cGAS/STING activation are implicated, are always associated with platelet enlargement and hyperreactivity." (PMID 38111039, 2023). "cGAS-STING is involved in the pathophysiology of cardiovascular disease and risk factors." (PMID 34381828, 2021). "Therefore, studying the role of inflammation caused by cGAS-STING pathway in cardiovascular diseases could provide a new therapeutic target for cardiovascular diseases." (PMID 36072862, 2022). "Considering the critical role of the cGAS-STING signaling axis in the pathophysiology of cardiovascular disorders, it is plausible to target this pathway to mitigate inflammatory responses, cellular senescence, and cell death as a therapeutic approach." (PMID 40461989, 2025). "We also focus on the potential roles of cGAS-STING inhibitors or agonists for cardiovascular diseases therapy, in order to provide useful insights into the precise treatment of CVDs." (PMID 40461989, 2025). "The cGAS-STING pathway has been implicated in vascular inflammation, playing arole in the pathogenesis of various cardiovascular diseases." (PMID 39076568, 2024). "The cGAS-STING pathway has been implicated in the development of endothelialdysfunction, a key pathological feature of various cardiovascular diseases.Activation of the cGAS-STING pathway in endothelial cells can trigger aninflammatory response." (PMID 39076568, 2024). "In summary, activation of the cGAS-STING pathway is involved in cardiovascular disease through a variety of cells, mediating inflammation and macrophage infiltration and participating in angiogenesis." (PMID 38164186, 2024). "This section offers a comprehensive review of the pathological processes in cardiovascular diseases, highlighting the regulatory role of inflammation driven by the cGAS-STING pathway." (PMID 38803502, 2024). "As previously emphasized, the cGAS-STING signaling pathway plays a pivotal role in the progression of various sterile cardiovascular diseases (CVDs)." (PMID 38803502, 2024). "The regulatory mechanism of cGAS-STING signaling pathway in experimental models of cardiovascular diseases." (PMID 38152400, 2023). "The pathological contribution of the cGAS/STING cascade to cardiovascular disorders is widely described." (PMID 37497006, 2023). "Herein, It's been aggregated that reported cGAS inhibitors were proven to exert protective effects in cardiovascular diseases." (PMID 36072862, 2022). "Emerging evidence supports that targeting cGAS-STING-mediated inflammation can be effective in treatment for cardiovascular diseases." (PMID 36072862, 2022). "Here, this section mainly discusses the cGAS or STING inhibitors applied in cardiovascular diseases." (PMID 36072862, 2022). "STING or cGAS inhibitors proven to exert protective effects in experimental models of cardiovascular diseases." (PMID 36072862, 2022). "This section mainly reviews the pathological process of cardiovascular diseases regulated by cGAS-STING-driven inflammation." (PMID 36072862, 2022). "This review focuses on the role of cGAS-STING-mediated sterile inflammation in cardiovascular diseases as well as the discovery of cGAS and STING inhibitors." (PMID 36072862, 2022). "The cyclic GMP-AMP synthase (cGAS)-stimulator of interferon genes (STING) signaling pathway has been suggested to contribute to the pathogenesis of cardiovascular diseases." (PMID 35538059, 2022).